H2BC12 (H2B clustered histone 12)
Description:
Core component of nucleosome. Nucleosomes wrap and compact DNA into chromatin, limiting DNA accessibility to the cellular machineries which require DNA as a template. Histones thereby play a central role in transcription regulation, DNA repair, DNA replication and chromosomal stability. DNA accessibility is regulated via a complex set of post-translational modifications of histones, also called histone code, and nucleosome remodeling. Has broad antibacterial activity. May contribute to the formation of the functional antimicrobial barrier of the colonic epithelium, and to the bactericidal activity of amniotic fluid.
Synonyms: H2BFT; HIST1H2BK; H2BFAiii; H2B/S; H2BK
Tractability: Small molecule: a structure with a bound ligand is known. PROTAC: UniProt records ubiquitination sites on it; ubiquitination databases record sites on it.
Gene: Protein-coding gene on chromosome 6 (27,137,298 to 27,146,857, reverse strand). Ensembl gene ENSG00000197903.
Subcellular location: Nucleus; Chromosome
Subcellular location (Human Protein Atlas): Nucleoplasm; Cytosol
Pathways (Reactome):
Gene expression (Transcription): B-WICH complex positively regulates rRNA expression; DNA methylation; ERCC6 (CSB) and EHMT2 (G9a) positively regulate rRNA expression; MLL4 and MLL3 complexes regulate expression of PPARG target genes in adipogenesis and hepatic steatosis; NoRC negatively regulates rRNA expression; PRC2 methylates histones and DNA; RNA Polymerase I Promoter Escape; RNA Polymerase I Promoter Opening; RUNX1 regulates genes involved in megakaryocyte differentiation and platelet function; RUNX1 regulates transcription of genes involved in differentiation of HSCs; Regulation of endogenous retroelements by KRAB-ZFP proteins; Regulation of endogenous retroelements by Piwi-interacting RNAs (piRNAs); Regulation of endogenous retroelements by the Human Silencing Hub (HUSH) complex; SIRT1 negatively regulates rRNA expression; Transcriptional regulation by small RNAs
Chromatin organization: CHD1 and CHD2 subfamily; CHD6, CHD7, CHD8, CHD9 subfamily; ChAHP complex assembly; HATs acetylate histones; HDACs deacetylate histones; Interaction of NuRD complexes with transcription factors; NuRD complex assembly
DNA Repair: Cleavage of the damaged purine; Cleavage of the damaged pyrimidine; Nonhomologous End-Joining (NHEJ); Processing of DNA double-strand break ends; Recognition and association of DNA glycosylase with site containing an affected purine; Recognition and association of DNA glycosylase with site containing an affected pyrimidine; Recruitment and ATM-mediated phosphorylation of repair and signaling proteins at DNA double strand breaks
Cell Cycle: Condensation of Prophase Chromosomes; Deposition of new CENPA-containing nucleosomes at the centromere; G2/M DNA damage checkpoint; Inhibition of DNA recombination at telomere; Packaging Of Telomere Ends
Developmental Biology: Activation of anterior HOX genes in hindbrain development during early embryogenesis; Chromatin modifications during the maternal to zygotic transition (MZT); Replacement of protamines by nucleosomes in the male pronucleus; Transcriptional regulation of granulopoiesis
Disease: Defective pyroptosis; Dengue Virus-Host Interactions
and 18 more pathways
Gene Ontology:
Molecular function: protein binding; DNA binding; structural constituent of chromatin; protein heterodimerization activity
Biological process: antibacterial humoral response; antimicrobial humoral immune response mediated by antimicrobial peptide; defense response to Gram-negative bacterium; defense response to Gram-positive bacterium; innate immune response in mucosa; killing of cells of another organism; chromatin organization
Cellular component: extracellular region; nucleosome; nucleus; nucleoplasm; chromosome
Genetic constraint (gnomAD): Loss-of-function variants: 6 observed, 5.76 expected, observed/expected ratio (o/e) 1.04, 90% interval 0.56 to 1.8. That is too few expected variants to judge how well the gene tolerates losing a copy. Missense variants: 119 observed, 158.93 expected, observed/expected ratio (o/e) 0.75, 90% interval 0.64 to 0.87. Synonymous variants: 132 observed, 70.99 expected, observed/expected ratio (o/e) 1.86, 90% interval 1.6 to 1.98.
Homologues: Orthologues: dog H2BC15 (100% identical). Paralogues in human: H2BC10 (99% identical), H2BC11 (99% identical), H2BC4 (99% identical), H2BC6 (99% identical), H2BC7 (99% identical), H2BC8 (99% identical), H2BC12L (98% identical), H2BC15 (98% identical), H2BC21 (98% identical), H2BC5 (98% identical), H2BC9 (98% identical), H2BC13 (98% identical), and 9 more.
Diseases named in the same sentence as H2BC12 in open-access papers:
H2BC12 is named in the same sentence as 25 diseases in open-access papers, as found by Europe PMC text mining. Sharing a sentence is not in itself a finding about the gene and the disease. The quoted sentences say what the papers report.
breast carcinoma (10 papers, 2016 to 2025). "In the CBD signaling, the key axis was formed by SUPT16H, SETD2, and H2BC12, which suggests epigenetic regulation by CBD in the restoration of an epithelial phenotype of breast cancer cells, providing new targets for anticancer therapy." (PMID 40429863, 2025).
glioma (9 papers, 2020 to 2025). A benign or malignant brain and spinal cord tumor that arises from glial cells (astrocytes, oligodendrocytes, ependymal cells). "ROC curve was plotted to evaluate the diagnostic significance of H2BC12 mRNA for gliomas." (PMID 35547391, 2022). "H2BC12 is a member of the histone H2B family, and its expression is correlated with positive clinical outcomes of glioma patients." (PMID 40429863, 2025). "Meanwhile, high H2BC12 levels were associated with IDH status, 1p/19q codeletion, primary therapy outcome, and the histological type of gliomas." (PMID 35547391, 2022). "Given that recent studies have defined an important role for H2BC12 in low-grade glioma, this study focuses on other members of the H2B gene family." (PMID 36387186, 2022). "The expression of H2BC12 mRNA and the corresponding clinicopathologic characteristics of 528 primary tumors were obtained from the glioma dataset; of these, 523 RNA-seq datasets were available." (PMID 35547391, 2022). "Several studies have shown that H2BC5, H2BC9, and H2BC11 are independent prognostic factors of cervical cancer, and H2BC12 is an independent prognostic factor for low-grade glioma." (PMID 36387186, 2022). "Here, H2B Clustered Histone 12 (H2BC12) was investigated in GII and GIII glioma tissue, assessing biomarkers for gliomas, associations with clinical characteristics, prediction survival outcome values, and the involved biological pathways." (PMID 35547391, 2022). "Here, we found that H2BC12 mRNA presented with high expression in gliomas compared with normal tissues, and its expression in GIII was also higher than in GII." (PMID 35547391, 2022). "Glioma tissues were collected to verify results from the TCGA dataset, and H2BC12 mRNA was detected by RT-qPCR." (PMID 35547391, 2022). "This demonstrated that H2BC12 mRNA is closely related to the clinicopathologic characteristics of gliomas, and H2BC12 might be involved in disease progression." (PMID 35547391, 2022). "Besides, The algorithm of the estimate package showed that the expression of H2B family genes, especially H2BC9, H2BC11 and H2BC12 was positively correlated with the presence of stromal cells in glioma, the level of immune cells and the purity of tumor cells." (PMID 36387186, 2022). "Collectively, H2BC12 mRNA expression is intimately correlated with clinicopathologic features, suggesting that H2BC12 might be involved in glioma progression." (PMID 35547391, 2022). "Relationship between H2BC12 mRNA expression and clinical characteristics in gliomas." (PMID 35547391, 2022). "Collectively, H2BC12 mRNA might serve as an important player in the initiation and development of gliomas." (PMID 35547391, 2022). "This implied that H2BC12 might be a therapeutic target or biomarker and that it is involved in promoting glioma progression." (PMID 35547391, 2022). "H2BC12, therefore, has promising application for the diagnosis and prognosis of gliomas." (PMID 35547391, 2022). "This indicated that H2BC12 might predict the survival outcome of gliomas, which was consistent with a previous study that showed that signatures based on histone gene family are potentially good indicators for the outcome of cervical cancer patients." (PMID 35547391, 2022). "Furthermore, the level of H2BC12 mRNA in GIII gliomas was higher than that of GII gliomas (p < 0.001)." (PMID 35547391, 2022). "All these findings indicate the potential important role of H2BC12 in gliomas progression." (PMID 35547391, 2022). "Finally, we conducted GSEA to uncover the H2BC12-related pathways in gliomas." (PMID 35547391, 2022). "These suggested that H2BC12 might be active in promoting glioma initiation." (PMID 35547391, 2022). "H2BC12 could be a potential prognostic marker and immunotherapy marker in gliomas." (PMID 35547391, 2022). "In addition, the H2BC12 mutation was not investigated in glioma patients and was very low in most brain tumors." (PMID 35547391, 2022).
glioma (continued). "This study identified the differentially up-regulated expression of H2BC12 in GII and GIII glioma tissue and proved its significant ability in predicting the adverse overall survival of GII and GIII gliomas patients." (PMID 35547391, 2022). "The significance of H2BC12 mRNA GII and GIII gliomas was also investigated." (PMID 35547391, 2022). "Our findings suggested that H2BC12 might be recognized as a promising biomarker for the prognosis of GII and GIII gliomas." (PMID 35547391, 2022).
ovarian carcinoma (3 papers, 2020 to 2022). A malignant neoplasm originating from the surface ovarian epithelium. "Previous bioinformatics analysis identified that high H2BC12 predicted adverse outcomes of breast, pancreatic, and ovarian cancers." (PMID 35547391, 2022).
Alzheimer disease (2 papers, 2019 to 2021). A progressive, neurodegenerative disease characterized by loss of function and death of nerve cells in several areas of the brain leading to loss of cognitive function such as memory and language. "For example, H3C2 plays an essential role in brain development in early embryonic development, and H2BC12 is involved in Alzheimer's disease." (PMID 34660567, 2021).
embryonic carcinoma (1 paper, 2022). "However, H2BC5 and H2BC12 were found to be hypermethylated in malignant pluripotent embryonic carcinoma, and H2BC12 was also shown to be hypermethylated in neuroblastomas." (PMID 36387186, 2022).
infertile (1 paper, 2023). "In fact, we have observed increased retention of histone proteins (H1-3, H1-4, H1-7, H2BC19P, H2BC11, H2BC12, H2BS1) in the spermatozoa of idiopathic infertile patients implying improper nuclear remodelling." (PMID 37261076, 2023).
Parkinson disease (1 paper, 2023). A progressive degenerative disorder of the central nervous system characterized by loss of dopamine producing neurons in the substantia nigra and the presence of Lewy bodies in the substantia nigra and locus coeruleus. "The H2BC12 gene encodes a subunit of histone H2B and has received relatively little attention in Parkinson’s disease research." (PMID 37908486, 2023). "This study demonstrates the significant value of constructing a diagnostic model using FLT1, ATP6V0E1, ATP6V0E2, and H2BC12, and their importance in the diagnosis of Parkinson's disease." (PMID 37908486, 2023). "This study reports for the first time the potential mechanisms and diagnostic value of FLT1, ATP6V0E1, ATP6V0E2, and H2BC12 in regulating the immune microenvironment in Parkinson's disease." (PMID 37908486, 2023).
tumor (7 papers, 2019 to 2023). "H2BC12 mRNA was examined in two cohorts, showing a significant upward trend in primary tumor tissue." (PMID 35547391, 2022). "In addition, tumor samples of each clinicopathologic subgroup were divided into two groups according to the median H2BC12 mRNA." (PMID 35547391, 2022). "In this study, we firstly obtained RNA-seq data documented in TCGA and matched normal samples from GTEx in the UCSC XENA database, demonstrating that H2BC12 mRNA significantly increased in tumor tissue compared to normal control." (PMID 35547391, 2022).
cancer (5 papers, 2020 to 2025). A tumor composed of atypical neoplastic, often pleomorphic cells that invade other tissues. "Based on the curated collection, there were six signaling pathways activated in H2BC12 overexpressed phenotype, including pathways in cancer, Wnt or the PI3K-AKT signaling pathway, DNA repair, cellular senescence, and DNA double-strand break repair." (PMID 35547391, 2022).
H2BC12 also shares sentences with these, for which no sentence is quoted: cervical carcinoma (3 papers); pancreatic cancer (3); brain tumors (1); esophageal adenocarcinoma (1); infectious disease (1); invasive ductal carcinomas (1); legionellosis (1); leukemia (1); low grade glioma (1); lung carcinoma (1); neuroblastoma (1); pancreatic ductal adenocarcinoma (1); prion disease (1); systemic lupus erythematosus (1); viral infection (1); Zika virus infection (1).